LOX (lysyl oxidase)
Diseases named in the same sentence as LOX in open-access papers (continued):
Sharing a sentence is not in itself a finding about the gene and the disease.
diabetes (22 papers, 2012 to 2025). "Diabetic skin shows elevated matrix metalloproteinases (MMPs) and lysyl oxidase (LOX) levels on dermis that lead to fragmentation and the accumulation of cross-linked collagen, thus resulting in the aging phenotype in the skin of diabetics." (PMID 40298628, 2025). "Only the LOX gene polymorphism was associated with the risk of single IA after adjusting for age, smoking status, diabetes mellitus, and hyperlipidemia." (PMID 34393991, 2021). "Collectively, these findings establish endothelial LOX/LOXL2 as core regulators of pathogenic glomerular signaling in diabetes and position Verbascoside as an enzymatically targeted precision therapy for DKD acting through the disruption of this specific LOX/LOXL2-mediated axis." (PMID 41355449, 2025). "This raises the possibility that LOX upregulation in diabetes could promote vascular BM thickening and play a pathogenic role in DR by both enzymatic and non-enzymatic mechanisms." (PMID 35563478, 2022). "Given that diabetes mellitus is negatively associated with AD, diabetes-induced LOX overexpression in the aorta may mediate this protective effect." (PMID 34307505, 2021). "The elevation of MMPs and LOX over the years is thought to result in the accumulation of fragmented and cross-linked collagen, and thus impairs dermal collagen structural integrity and mechanical properties in diabetes." (PMID 27104752, 2016). "However, only the association of LOX rs10519694 and IA remained significant after adjusting for age, smoking status, diabetes mellitus, and hyperlipidemia (recessive and additive models: OR, 3.88; 95%CI, 1.12–13.47; p = 0.033; and OR, 1.56; 95%CI, 1.05–2.34; p = 0.030, respectively)." (PMID 34393991, 2021). "Elevation of MMPs and LOX over the years is thought to result in accumulation of fragmented and cross-linked collagen fragments, and thus may contribute to aged-appearing skin in diabetes." (PMID 27104752, 2016). "With the mediation of TNF-α, LOX was reportedly downregulated in inflammatory conditions such as diabetes and osteoporosis, thereby suppressing cell growth and reducing the pluripotent cell pool." (PMID 38390397, 2023). "This is consistent with the finding of increased LOX-dependent crosslinking in skin collagen in patients with diabetes." (PMID 34746916, 2021). "The role of TNF-α is pleiotropic; it inhibits the functions of LOX in diabetes, osteoporosis and rheumatic arthritis, but also upregulates LOX in myocardial fibrosis and in esophagitis patients." (PMID 32708046, 2020). "In an inflammatory context, LOX plays a role in diminishing pluripotent mesenchymal cell pools which are relevant to the pathology of diabetes, osteoporosis and rheumatoid arthritis." (PMID 32708046, 2020). "Overall, studies conducted with in vitro cell culture models and animal models of diabetes suggest that excess LOX is likely involved in the pathogenesis of diabetic retinopathy." (PMID 31546618, 2019). "As mounting evidence suggests increased LOX activity in diabetes, little is known about LOX levels in the diabetic vitreous." (PMID 31546618, 2019). "Several studies using cell culture and animal models of diabetes indicate that HG or diabetes significantly increases the expression and activity of LOX in renal, pulmonary, and retinal tissues." (PMID 31546618, 2019). "Data presented here, performed in C57BL6 mice, osteoblasts, and MC3T3‐E1 cells, identify a novel gut/bone metabolic relationship that regulates osteoblast LOX that is dysregulated in diabetes, and importantly is amenable to therapeutic intervention." (PMID 31687648, 2019). "Further work to create relevant genetic mouse models are planned to further investigate the newly discovered relationships between diabetes, GIP, dopamine, LOX, and bone structure in diabetes." (PMID 31687648, 2019).
diabetes (continued). "Animal studies have shown diabetes-induced lysyl oxidase (LOX) upregulation promotes blood-retinal-barrier breakdown and retinal vascular cell loss associated with diabetic retinopathy (DR)." (PMID 31546618, 2019). "Histopathological examination of LOX expressions may be a way to identify periodontal diseases induced by diabetes." (PMID 36134856, 2022). "Here, we found that LOX is profoundly downregulated in bone in diabetes." (PMID 31687648, 2019). "Our results show a profound downregulation of LOX mRNA in diabetic bone, supporting our hypothesis that decreased LOX could be responsible for the decreased bone quality seen in diabetes." (PMID 31687648, 2019). "A recent study from our lab has shown that HG- or diabetes-induced LOX upregulation promotes apoptosis in retinal vascular cells, and that normalization of LOX overexpression using a siRNA strategy in vitro or through a LOX heterozygous knockout animal model in vivo prevented apoptosis." (PMID 31546618, 2019). "Data indicate that the incretin (gastric hormone) known as glucose‐dependent insulinotropic polypeptide (GIP) that is anabolic to osteoblasts strongly upregulates LOX, and that this regulation is disrupted in the streptozotocin‐induced model of diabetes in mice." (PMID 31687648, 2019). "Although LOX‐dependent biosynthetic crosslinks in bone collagen are deficient in diabetic bone, the expression and regulation of bone LOXs in diabetes have not been comprehensively studied." (PMID 31687648, 2019). "HG or diabetes is known to induce excess extracellular matrix synthesis and upregulate LOX, which could lead to accumulation and stiffening of the extracellular matrix." (PMID 31546618, 2019). "We propose that interference with lysyl oxidase expression under excess inflammatory conditions such as those that occur in diabetes, osteoporosis, or rheumatoid arthritis can result in a diminished pool of pluripotent cells which ultimately contributes to osteopenia." (PMID 24971753, 2014). "Excess TNF-α levels in inflammatory diseases including diabetes may contribute to osteopenia by inhibiting the proliferation of pluripotent cells by down-regulating lysyl oxidase." (PMID 24971753, 2014). "Several studies have reported elevated LOX activity and increased collagen cross-linking in diabetic tissues such as the lungs of diabetic rats and the skin of diabetic patients where elevated LOX activity correlated with duration of diabetes, glycemic control, and long-term complications." (PMID 35563478, 2022). "The data supports our previous findings, showing high glucose or diabetes upregulates LOX expression in retinal endothelial cells in vitro, and in vascular cells of retinal capillaries from diabetic rats and mice, and that upregulation of LOX promotes cell monolayer permeability." (PMID 31546618, 2019). "In patients with diabetes, increased LOX activity has been reported in skin biopsies and vitreous samples from the eye as evidenced from increased LOX-mediated collagen crosslinks and early glycation products, glucitolyllysine and glucitolylhydroxylysine, which are indirect measures of LOX activity." (PMID 31546618, 2019). "In both type 1 and type 2 diabetes mellitus, increased plasma concentrations of PGE2, HETEs, and LTs (derived from AA) have been reported, indicating enhanced COX-2 and LOX activities." (PMID 40005295, 2025). "Our study also provides the first evidence of increased serum dopamine levels in diabetes, and further shows that dopamine inhibits GIP‐stimulated LOX expression in osteoblasts." (PMID 31687648, 2019). "After we had established that diabetic mice had decreased LOX levels, aberrant collagen structure, and decreased trabecular bone volume and defective trabecular structure, we next sought to investigate specific molecular mechanisms occurring in diabetes that could result in these effects on bone." (PMID 31687648, 2019).
diabetes (continued). "In vivo and in vitro studies support that diabetes results in elevated circulating peripheral dopamine, likely also derived from the gut, and is responsible for blocking GIP signaling and LOX levels in osteoblasts." (PMID 31687648, 2019). "The results suggest that LOX, HIF1α, THBS1, TGFβ2, and ITGβ1 may be involved in the diabetes‐induced downregulation of FGF9, thus promoting the development of renal EMT." (PMID 40977522, 2025). "To confirm that decreased GIP signaling is specifically due to dopamine and not some other signaling dysregulation in diabetes, we rescued GIP signaling and LOX production in diabetic osteoblasts by inhibiting dopamine receptor activity." (PMID 31687648, 2019).
fibrosis (22 papers, 2016 to 2026). the formation of excess fibrous connective tissue in an organ or tissue in a reparative or reactive process. "Fibrosis and cancer intersect through the lysyl oxidase (LOX) enzyme, both sharing a disrupted extracellular matrix (ECM) microenvironment." (PMID 40661776, 2025). "Previous studies have reported increased LOX-IR in the skin of patients with systemic scleroderma, a disease characterized by fibrosis." (PMID 39859514, 2025). "The anti-fibrotic action of lysyl oxidase inhibitors has been demonstrated in a variety of preclinical cancer and fibrosis models." (PMID 35205728, 2022). "Enzymes belonging to the lysyl-oxidase (LOX) family are responsible for collagen as well as elastin crosslinking in pathological conditions like fibrosis." (PMID 32296422, 2020). "Significantly increased LOX activity is observed in sera of patients with hepatic diseases such as chronic hepatitis, fibrosis, and cirrhosis, implying the potential of LOX family as a biomarker for liver fibrosis." (PMID 27800489, 2016). "Lysyl oxidase (LOX) fulfills a critical function in vascular fibrosis and extracellular matrix (ECM) remodeling by catalyzing the oxidation of lysine residues in collagen and elastin, thereby facilitating ECM cross-linking and contributing to vascular wall stiffening." (PMID 40661776, 2025). "Moreover, lysyl oxidase (LOX), a copper-dependent enzyme required for collagen crosslinking, is upregulated in fibrosis, further contributing to copper accumulation." (PMID 40390111, 2025). "Fibrosis is characterized by increased LOX and TGF-β which are both associated with AVF non-maturation." (PMID 36926045, 2023). "(iv) Bioinformatics and gain- or loss-of-function analysis identified RMST as a ceRNA of miR-24-3p, which could regulate cardiac fibrosis through the LOX signaling pathway." (PMID 37441584, 2023). "Thus, LOX/LOXLs contribute to cardiac fibrosis, but are also active players involved in the cellular mechanisms underlying cardiac dysfunction and disease progression." (PMID 31766500, 2019). "The targeting of LOX enzymes, using function-blocking mAbs, has long shown promise in normalising a pathologically stiff ECM in mouse xenografts and fibrosis models; the targeting of LOX can reduce stiffness, desmoplasia, invasion, and metastasis." (PMID 38791926, 2024). "In one study of bleomycin-induced fibrosis in mice, MSC improved survival by diminishing TNF-α, TGF-β1, and LOX levels, and finally the inflammation process in IPF." (PMID 36588784, 2022). "Elevated activity of LOX has been confirmed for other models of IPF, for example in paraquat-induced fibrosis." (PMID 35205728, 2022). "In contrast to lung tissue from control treated mice, LOX and LOXL2 were highly induced in the BLM-induced fibrosis model." (PMID 28273952, 2017). "Current FDA-approved anti-fibrosis drugs: Nintedanib and Pirfenidone, are not targeting the lysyl oxidase mediating collagen stabilization." (PMID 36894533, 2023). "In addition, we analysed in HDFa fibroblasts the involvement of diverse fibrosis-related genes in the EXP3179-induced LOX inhibition, by using the RT2 ProfilerTM PCR Array Human Fibrosis." (PMID 28157237, 2017).
keratoconus (21 papers, 2011 to 2026). A degenerative, structural disorder of the eye, characterized by a cone-shaped protrusion of the cornea. "Subsequent replication in case–control cohorts of European, Chinese, and Iranian patients confirmed the association of a LOX variant with keratoconus." (PMID 41595486, 2026). "The association between LOX and keratoconus is supported by replicated findings across multiple populations and is further strengthened by functional evidence demonstrating reduced LOX expression and activity in keratoconic corneas." (PMID 41595486, 2026). "Given the relevance of the functional deficiency of LOX enzymes in keratoconus, LOXL1 is proposed as a possible candidate gene." (PMID 37895187, 2023). "We found evidence that SNPs associated with keratoconus often alter methylation of many genes, including LOX, PDDC1, SMAD3, HOXB1, KLF5, and BANP." (PMID 33649486, 2021). "A strong association of LOX variant rs2956540 with keratoconus was identified in the combined dataset of Caucasians and Chinese cohorts (P = 1.43E-08) and there was no heterogeneity (I2 = 0)." (PMID 26713757, 2015). "Several case-control studies have been performed to examine the association of genetic variants in lysyl oxidase (LOX) with keratoconus." (PMID 26713757, 2015). "In conclusion, the current study provided substantial evidences that two LOX variants, rs2956540 and rs10519694 were significantly associated with keratoconus." (PMID 26713757, 2015). "Our study highlighted the importance of LOX locus to keratoconus susceptibility, while more efforts are required to get a comprehensive understanding on the detailed mechanisms." (PMID 26713757, 2015). "Two SNPs (rs10519694 and rs2956540) in LOX showing nominal genome-wide significance were associated with keratoconus by family-based association testing that were also found to be significantly associated with keratoconus in case-control cohorts." (PMID 25254113, 2014). "Therefore, in order to provide a reliable evaluation of the association between SNPs in LOX and keratoconus susceptibility, we performed meta-analysis, which involved the largest sample size to date with a total of 1,467 keratoconus cases and 4,490 controls." (PMID 26713757, 2015). "Therefore, the aim of the current study was designed to clarify the association between LOX variants and keratoconus susceptibility." (PMID 26713757, 2015). "It was demonstrated that changes in LOX distribution and its decreased activity might be potential reasons for the inadequate collagen cross-linking in keratoconus, which is a hallmark of this disease." (PMID 26713757, 2015). "Meta-analysis of allelic association of LOX polymorphisms with keratoconus." (PMID 26713757, 2015). "Although this evidence highlighted the potential contribution of LOX to keratoconus susceptibility, the results were inconclusive and great heterogeneity might exist across populations." (PMID 26713757, 2015). "This meta-analysis suggested that two LOX variants, rs2956540 and rs10519694, may affect individual susceptibility to keratoconus, while distinct heterogeneity existed within this locus." (PMID 26713757, 2015). "However, due to the limited number of studies that evaluating the association of LOX variants to keratoconus susceptibility, currently we cannot perform further stratified analysis based on ethnicity, subclinical forms, or sample size." (PMID 26713757, 2015). "Also, VSX1, SOD1, and LOX genes are associated with keratoconus in some studies." (PMID 40002778, 2025). "Therefore, if LOX expression is upregulated in corneal cells under hyperglycemia, this could explain why individuals with DM have a lower risk of developing keratoconus." (PMID 38020157, 2023).
keratoconus (continued). "In 2012 a GWAS project consisting of 526 keratoconus cases and 3,842 controls, together with 70 keratoconus families with a total of 146 patients and 161 unaffected family members identified lysyl oxidase (LOX) as a potential susceptibility gene for keratoconus in American Caucasians." (PMID 26713757, 2015). "For example, a reduction in the expression of the LOX gene and protein has been observed in blood samples from keratoconus (KC) patients, and alterations in LOX expression in corneal tissue have also been reported." (PMID 40217908, 2025). "The whole-genome association studies have also contributed to the identification of several important genetic mutations associated with keratoconus, including the TGFBI, TCEB1, CAST, COL8A1, and LOX genes." (PMID 40002778, 2025). "Two additional new polymorphisms in LOX 5'UTR region (–116C > T and –58C > T) were found in two patients presenting with advanced keratoconus and were predicted to modulate or create donor/acceptor splice sites in LOX transcripts." (PMID 32308947, 2020). "Donor genomic DNA extracted from blood samples was screened for 5'UTR, exonic LOX, and SOD1 variants in a subset of 26 patients presenting with advanced keratoconus (KISA > 1000% and I–S > 2.0) by Sanger sequencing." (PMID 32308947, 2020). "Lysyl oxidase (LOX) is significantly decreased within keratoconus as well as in conditions including Down's syndrome, where the prevalence of keratoconus is enhanced." (PMID 30053442, 2018). "Lysyl oxidase activity, an enzyme involved in cross linking, is decreased in the stroma of keratoconus corneas." (PMID 28315339, 2017). "All of these evidences suggested the critical involvement of LOX in the pathogenesis of keratoconus, and also implying the importance of deciphering the genetic code of LOX in contributing keratoconus susceptibility." (PMID 26713757, 2015). "In this study, we report the mutational analysis results for VSX1, LOX, SPARC, TIMP3, and SOD1, performed in a large cohort of Italian subjects affected by sporadic and familial keratoconus." (PMID 21976959, 2011). "In keratoconus, a disease characterized by irregular astigmatism resulting in significant visual impairment, LOXL3 expression is downregulated, as well as LOXL2 and LOXL4 expression, suggesting that LOX members may be involved in keratoconus pathogenesis." (PMID 31340433, 2019). "The LOX (collagen crosslinking enzyme lysyl oxidase) gene responsible for the crosslinking of collagen and elastin is considered a potentially dependable factor in the development of keratoconus, leading to a weakened corneal structure." (PMID 30245588, 2018). "The reduced LOX availability would reduce the tropoelastin cross-linking that is required for true elastic fibre assembly, so it is likely that this would affect the presence of true elastic fibres in the peripheral keratoconus cornea also." (PMID 30053442, 2018). "Differential gene expression analysis in debrided corneal epithelia of patients with keratoconus showed dysregulations of LOX and collagens - collagen I alpha 1 (COLIA1) and collagen IV alpha 1 (COLIVA1) and an elevated expression of matrix metalloproteinase 9 (MMP9)." (PMID 27493978, 2016). "In addition, a significant reduction in LOX transcript was observed in corneal epithelia of keratoconus patients compared to healthy donors, and LOX activity in keratoconus tears was found to correlate with disease severity." (PMID 26713757, 2015). "Furthermore, LOX expression and activity are reduced in keratoconus corneas." (PMID 39869570, 2025). "In addition, the proximal location of SPARC to the LOX gene, residing on chromosomes 5q31.3-q32 and 5q23.2, respectively, could also suggest its contribution to keratoconus." (PMID 37895187, 2023). "Similarly, other candidate genes identified by GWAS including HGF, RAB3GAP1, LOX, MPDZ, NFIB, BANP, and ZNF469 may be important risk factors for keratoconus and require replication studies in other populations." (PMID 25254113, 2014).